SRSF1 (serine and arginine rich splicing factor 1)
Diseases named in the same sentence as SRSF1 in open-access papers (continued):
Sharing a sentence is not in itself a finding about the gene and the disease.
cancer (197 papers, 2010 to 2026). A tumor composed of atypical neoplastic, often pleomorphic cells that invade other tissues. "In summary, SRSF1 was relevant to cancer-related signaling pathways and associated with cancer progression." (PMID 38735973, 2024). "We analyzed several cancer-associated genes with experimentally verified splice variations that are affected by SRSF1 overexpression." (PMID 36599821, 2023). "The upregulation of SRSF1 and SRPK1 (upstream regulator of SRSF1) promotes the generation of the aberrant splice variant VEGF165b, leading to more aggressive PCa with enhanced cancer growth." (PMID 37370750, 2023). "The high expression level of SRSF1 has been shown to confer poor prognosis in a variety of cancers, and the underlying mechanisms were characterized." (PMID 37206090, 2023). "In this study, the cancer cells were engineered to bear disturbed splicing by PlaB or SRSF1 overexpression, which represents an accelerated mutation (antigen generation) process during cancer evolution." (PMID 37097746, 2023). "In the literature, phenotypes linked with SRSF1 overexpression causing dysregulation of alternative splicing have been associated with cancer." (PMID 37071997, 2023). "More than a shred of evidence is in favor of the proto-oncogenic role of SRSF1 indicates that it is associated with different cancers and regulates cell proliferation and apoptosis." (PMID 35027535, 2022). "SRSF1 as a classic member of the SR protein family, has been reported in several cancers and is associated with poor prognosis." (PMID 33992102, 2021). "Collectively, our study highlights the biological and clinical significance of SRSF1 in BRCA, including the SRSF1-dependent regulation of cancer-associated AS events, and investigates the underlying regulatory mechanisms in detail." (PMID 33992102, 2021). "The Serine and Arginine-Rich Splicing Factor 1 (SRSF1) has a proto-oncogenic function, being associated with angiogenesis and frequently overexpressed in many human malignant neoplasms." (PMID 34207798, 2021). "Altogether, NEAT1 is an excellent example of a cancer-associated lncRNA, which is collectively regulated by multiple RBPs that can either enhance its stability (HuR and SRSF1) or promote its degradation (AUF1 and PABPN1)." (PMID 32340118, 2020). "The rationale of this analysis was overexpression of SRSF1 gene, encoding an alternative splicing regulator, in different cancer types, described as one of the features promoting cancerogenesis." (PMID 30126426, 2018). "An increase in SRSF1 expression was frequently identified in different cancers and was linked to its pro-oncogenic potential." (PMID 29283381, 2017). "Consistently, several splicing factors were found to be mutated or significantly changed in expression between cancers and normal tissue, including SRSF1, QK1, RBM4, RBM5/6/10, and hnRNP A2." (PMID 25749525, 2015). "SRSF1 is an important proto-oncogene due to its role in the alternative splicing regulation of several cancer-associated genes." (PMID 25845590, 2015). "HnRNP A2/B1, PTB, and SRSF1 were reported to act oncogenes due to their influence of inducing cancer-associated transcripts." (PMID 26506517, 2015). "Clear experimental evidence for tumor-promoting effects of SRSF1-induced alternative splicing variants has been provided but the genome-wide scale of its effects on cancer cell biology remains to be described." (PMID 26273603, 2015). "Here, we selected other six U2-dependent spliceosome genes previously shown to have cancer-associated mutations (SRSF1, SRSF2, SF3A1, SF3B1, SF1 and PRPF40B), and screened 17 putative tag single nucleotide polymorphisms (tagSNPs) in these genes." (PMID 26498691, 2015).
cancer (continued). "The SRSF1 gene itself is amplified in some cancer cells, and cancer-associated changes in the expression of MYC also increase SRSF1 gene expression." (PMID 23935626, 2013). "In cancer cells of other tissues, SRSF1 modulates the expression of splice variants of the BIN1 and BIM genes that lack proapoptotic functions." (PMID 23983695, 2013). "In fact, SRSF1 has several RNA targets in pre-mRNAs that are transcribed from genes implicated in cancer." (PMID 24101931, 2013). "Overexpression of SRSF1 promotes the growth of breast cancer cells and drives the alternative splicing of isoforms associated with various cancer hallmarks such as apoptosis (e.g., BIN1 and BIM), proliferation (e.g., RON, MKNK2, and S6K1), and DNA damage response (e.g., PTPMT1)." (PMID 37510283, 2023). "Abnormal splicing of ER, HER2, CEACAM1, and SRSF1 has been reported to contribute to breast tumorigenesis and prognosis, which could be an underlying target for cancer treatment." (PMID 32079071, 2020). "Importantly, the intracranial injection of an SRSF1-targeted DRO in a GBM mouse model decreased the oncogenic properties of cancer cells by reverting the splicing of oncogenic splice variants of SRSF1-target genes (INSR, U2AF1, MKNK2, USP8)." (PMID 31861467, 2019). "Previously SRSF1 has been identified as a proto-oncogene with increased expression in a wide variety of tumours, and in addition has been demonstrated to be involved in cancer associated changes in alternative splicing." (PMID 23284704, 2012). "Moreover, SRSF1 over expression in different types of cancer is associated with worse prognosis." (PMID 32819370, 2020). "Tumor growth suppression was linked to a higher presence of Srsf1-deficient tumor-infiltrating effector T cells; Thus, Srsf1 negatively regulates CD8+ T cell functional potency in cancer." (PMID 39837814, 2025). "For instance, the protein SRSF1 is often found at high levels in colorectal and other solid tumors, where it helps cancer cells grow and spread." (PMID 41514860, 2025). "Serine arginine-rich splicing factor 1 (SRSF1) is a key oncogenic splicing factor in various cancers, promoting abnormal gene expression through post-translational regulation." (PMID 39837814, 2025). "Several splicing factors, like polypyrimidine tract binding protein (PTBP1), SR protein (SRSF1), and heterogeneous nuclear ribonucleo-proteins (hnRNPs), are highly expressed in cancer." (PMID 39863145, 2025). "Reports indicated that lncRNAs participate in cancer cell proliferation, invasion, and apoptosis by binding to SRSF1." (PMID 40537877, 2025). "Previous studies showed similar effects for the splicing factors BUD31 and SRSF1, the knockdown of which leads to inhibited proliferation and increased apoptosis in other cancer types." (PMID 39212334, 2025). "By regulating the expression of FOXO1 and CD38, inactivating SRSF1 in T cells dramatically increases the cytotoxicity of CD8 + T cells in malignancies." (PMID 39837814, 2025). "The cell-autonomous roles of SRSF1 in cancer carcinogenesis have been the focus of these investigations." (PMID 39837814, 2025). "Hyperactive MYC promotes inflammation and cancer transformation by inhibiting the negative regulation of Splicing Factor SRSF1 in AP." (PMID 40699778, 2025). "Our findings demonstrate that inhibiting the splicing factor SRSF1 can overcome barriers to effective cancer immunotherapy." (PMID 39837814, 2025). "Although there are several RNA-Seq databases available for exploring SRSF1-related changes in cancer, the knowledge regarding the AS networks regulated by SRSF1 in the heart is still limited." (PMID 39578852, 2024). "In this study, we conducted in vitro experiments to examine the cancer-related functions of SRSF1 in OS." (PMID 38735973, 2024). "SRSF1, a member of Serine/Arginine-Rich Splicing Factors (SRSFs), has been observed to significantly influence cancer progression." (PMID 38735973, 2024).
cancer (continued). "SRPK1 is a poor prognostic indicator in colorectal cancer in which it modulates SRSF1-mediated MKNK2 alternative splicing and is required for the expression of the cancer-associated splice variant RAC1B." (PMID 36895328, 2023). "One of the most widely studied SR protein splice factors is SRSF1, a splice factor with a well-established involvement in cancer." (PMID 36895328, 2023). "Serine/arginine-rich splicing factor 1 (SRSF1) is a proto-oncogene that is frequently overexpressed in various types of cancers." (PMID 37370750, 2023). "SRSF1 is overexpressed in many cancers, including breast, lung, and colon, via copy number gain and altered expression regulation." (PMID 37510283, 2023). "We identified distinct genes including KLK4, FN1, PBOV1, TPM2, and FLNA which are known to be involved in PCa pathways along with IGF1, TPD52, and SRSF1 that are involved in different cancer pathways." (PMID 37218885, 2023). "Although SRSF1 and hnRNPA1 are both frequently upregulated in cancer, they have opposite functions in AS events." (PMID 37988165, 2023). "We have shown that targeting an individual oncogenic splicing factor, SRSF1, impairs cancer progression through a variety of mechanisms." (PMID 35589755, 2022). "Its relationship with many cancers has been noticed, and SRSF1 is the best studied one, which has been revealed overexpressed in various cancers." (PMID 35069733, 2022). "Reduced SRSF1 expression was associated with a corresponding reduction in LGR5 suggesting that in human cancer, as in our mouse models, SRSF1 mediates stem cell function." (PMID 35589755, 2022). "SRSF1 regulates the alternative splicing and functions of the target genes involved in cancer progression." (PMID 35027535, 2022). "SRSF1 was confirmed to be a cancer promoter that can effectively promote the proliferation and invasion of cancer cells." (PMID 35712125, 2022). "The negative regulator of exon 20 skipping that we identified, SRSF1, is known to be upregulated in many cancers." (PMID 35202654, 2022). "Consistent with previous studies, the RBPs PTBP1 and SRSF1 were differentially upregulated in 6 and 3 cancer types, respectively." (PMID 35654793, 2022). "For instance, some known factors, such as SRSF1, have been described as overexpressed in cancer, leading to malignant transformation by an alternative splicing of genes involved in proliferation and apoptosis." (PMID 34439272, 2021). "Strikingly, oncogenic roles of SRSF1 and the landscape of AS events regulated by SRSF1 have been observed in several cancers." (PMID 33992102, 2021). "SRSF1 protein has been reported to regulate apoptotic control in human cancer cells through alternative splicing pathway." (PMID 34099633, 2021). "Consistently, the expression level of SRSF1 is inversely correlated to LC3 level in clinical cancer samples." (PMID 33664238, 2021). "Taken together, our study highlights mechanistic insights of alternative splicing in autophagy, and provides a new regulatory role of SRSF1 in tumorigenesis, offering a novel avenue for potential cancer therapeutics." (PMID 33664238, 2021). "As showed SRSF1 mediating the aberrant AS of BIN1 in NSCLC in our previous study, SRSF1 protein caught our attention for its role in splicing regulation in cancers." (PMID 34099633, 2021). "Predictably, an increase in SRSF1 expression in cancers is correlated with the appearance of new aberrant RNA isoforms and poor prognosis." (PMID 34769047, 2021). "Our study not only provides mechanistic insights of alternative splicing in autophagy regulation but also discovers a new regulatory role of SRSF1 in tumorigenesis, thereby offering a novel avenue for potential cancer therapeutics." (PMID 33664238, 2021).
cancer (continued). "Splicing is considered the main mechanism by which circRNAs originate, and SRSF1 is upregulated and functions as an oncoprotein in several cancers." (PMID 33858489, 2021). "SRSF1 is also targeted by miR-766-3p, a well-characterized tumor suppressor or inducer in several types of cancers, which is often markedly downregulated in cancers, leading to the overexpression of SRSF1." (PMID 34769047, 2021). "Serine- and arginine-rich splicing factor 1 (SRSF1)-mediated AS events are the most important molecular hallmarks in cancer." (PMID 34099633, 2021). "SRSF1 is a known pleiotropic nucleus-to-cytoplasm shuttling protein, involved in the development of several human cancers." (PMID 33562358, 2021). "Gemcitabine treatment of cancer cells eventually elevated splicing factor SRSF1, thus inducing an AS of the MAP kinase-interacting serine/threonine-protein kinase 2 (MNK2) gene towards its MNK2b variant." (PMID 34356101, 2021). "For instance, miR-7 prevents the translation of SRSF1 mRNA and decreases SRSF1-mediated AS, repressing cancer cell survival." (PMID 33407694, 2021). "Most importantly, knockdown of SRSF1 inhibits Gefitinib-resistant cancer cell progression at least partially through activating autophagy." (PMID 33664238, 2021). "The 3′UTR of SRSF1 possesses several miRNA targets, and coincidentally, the miRNAs that target SRSF1 are downregulated in many cancers." (PMID 34769047, 2021). "When overexpressed, SRSF1 acts as a proto-oncogene by inducing alternative RNA splicing in multiple genes that operate in the apoptotic pathway, promoting cancer establishment or progression." (PMID 34769047, 2021). "Together, knockdown of SRSF1 inhibits cancer progression partially through activating autophagy, providing a new mechanism for SRSF1 in tumorigenesis." (PMID 33664238, 2021). "SRSF1 is known to be involved in the expression of many cancer promoting genes as well as in the expression of pro-apoptotic isoforms of Bcl-x, RON, and MCL-1." (PMID 34944633, 2021). "By using ESEFinder 3.0 web tool, we were able to identify a putative ESE responsive to the human SRSF1, a member of the SR family of splicing regulators, which is frequently upregulated in different cancers." (PMID 33918758, 2021). "The functions of SRSF1 have been extensively studied in immortalised and cancer cells, where overexpression leads to altered splicing functions linked to transformation and oncogenesis." (PMID 34376242, 2021). "To verify the involvement of SRSF1 in exosome miRNA enrichment in cancer cells, we also exogenously overexpressed SRSF1 in PANC-1 cells." (PMID 32819370, 2020). "For this purpose, we analyzed the RNA sequences of the miRNAs highly enriched in cancer exosomes and regulated by SRSF1, using the bioinformatics tool MEME Suite." (PMID 32819370, 2020). "As control cells are hardly affected by SF2 silencing, SRSF1 represents a promising target for cancer therapy." (PMID 32599686, 2020). "Transfection of specific decoy oligonucleotides into cancer cells targeting SRSF1-binding resulted in changes in splicing of known targets of SRSF1, including MKNK2." (PMID 32481522, 2020). "The protein serine and arginine-rich splicing factor 1 (Srsf1) is a proto-oncogene that can act as an oncoprotein, and is an important target for cancer therapy, as it is overexpressed in many tumors." (PMID 32630349, 2020). "In summary, we have demonstrated that SRSF1 binds to a specific motif in the miR-1246 sequence and is significantly involved in selective exosome miRNA enrichment in cancer cells." (PMID 32819370, 2020). "The fact that a decoy motif was able to compete with the miR-1246 probe for binding to SRSF1 indicates a possibility that decoy motifs can be applied to alter exosome miRNA enrichment or exosome miRNA signaling in cancer cells." (PMID 32819370, 2020).
cancer (continued). "Among the RBPs identified, several were selected based on their detection intensity, relevance to extracellular vesicles, and reported connections to human cancer, including SRSF1, EIF3B, and TIA1." (PMID 32819370, 2020). "Given that SRSF1 acts as an oncoprotein and its inhibition by decoy oligonucleotides activated the p38-MAPK stress pathway, we predicted that treatment of cancer cells with SRSF1 decoy oligonucleotides would reverse the transformed phenotype of these cells." (PMID 30962446, 2019). "In ductal but not lobular tumors, significant inverse correlations were observed between the tumor levels of miR-10b and miR-30c and the mRNA levels of cancer-relevant target genes SRSF1, PIEZO1, MAPRE1, CDKN2A, TP-53 and TRA2B, as well as tumor grade." (PMID 30658617, 2019). "We also show that inhibition of SRSF1 with decoy oligonucleotides has an effect on the oncogenic properties of cancer cells and identified that this occurs through activation of the p38-MAPK pathway." (PMID 30962446, 2019). "SRSF1 is a protein involved in many biomolecular functions and its expression is known to be upregulated in several cancers." (PMID 30736462, 2019). "Since AKT signaling is often constitutively activated in cancers, such as lung cancer, this leads to constitutive phosphorylation of SRSF1 and deregulated expression of Caspase 9a/9b." (PMID 30246013, 2018). "SRSF1 (also known as SF2/ASF) is the first splicing factor to be identified as a proto-oncogene in human cancers." (PMID 30463359, 2018). "Previous studies revealed that SRSF1 is up-regulated in different types of human cancers, including colon, breast, thyroid, small intestine, kidney and lung cancers." (PMID 30463359, 2018). "For example, overexpression of alternative splicing regulator, SRSF1, detected in different cancer types, was postulated to promote cancerogenesis." (PMID 30126426, 2018). "SRSF1 is a key cancer driver, as demonstrated by the profound tumor-suppressive effect of specific SRSF1 knockdown in SRSF1-amplified or overexpressed SCLC models." (PMID 27093186, 2016). "Only the phosphorylation of SRSF1, which has been associated with proximal splicing of VEGF‐A in cancer cells and podocytes, was increased by VEGF‐B over this time period." (PMID 26957058, 2016). "One group of identified target genes is formed by the apoptosis regulators BIN1, BCL2L11 (BIM), BCL-XL, ICAD, and MCL1, with SRSF1 overexpression in cancer cells promoting the formation of their respective antiapoptotic splice variants." (PMID 26273603, 2015). "Two apparently opposing consequences of SRSF1 overexpression on cancer cell biology have been described: the induction of oncogene-induced senescence and the malignant transformation of cells." (PMID 26273603, 2015). "Further, the protein SRSF1 is up-regulated in cancer and its transcription is activated by the prooncogenic transcription factor Myc." (PMID 26308848, 2015). "In summary, these data provide insights on the complex role of SRSF1 in the control of gene expression and its implications in cancer." (PMID 24842991, 2014). "Myc upregulation in cancer leads to downstream increases in both SRSF1 mRNA and SRSF1 protein expression." (PMID 23935626, 2013). "It is also important to mention that SRSF1, a well-known target of SRPKs, is upregulated in human cancers and functions as an oncogene." (PMID 24069033, 2013). "Here, we review these important principles for SRSF1 and then apply these principles to gauge the likely effect of the Tra2β protein on cancer-specific gene expression." (PMID 23935626, 2013). "From these results, we concluded that SRSF1 and SRSF9 are required not only for Wnt-induced but also tumorigenic β-catenin accumulation in cancer cells harbouring mutations that impair β-catenin degradation." (PMID 23592547, 2013).